ALK (ALK receptor tyrosine kinase)
Diseases named in the same sentence as ALK in open-access papers (continued):
Sharing a sentence is not in itself a finding about the gene and the disease.
neuroblastoma (continued). "Overall, these preclinical data support the implementation of a phase 1 clinical trial to test ALK.CAR‐T cells in combination with lorlatinib in children with refractory/relapsed neuroblastoma." (PMID 38877641, 2024). "In conclusion, we present an NB-ALK sequencing panel for monitoring disease at subclinical levels in patients with ALK-driven neuroblastoma." (PMID 39177282, 2024). "Preclinical evaluations of combinations of a MEK inhibitor with a BET bromodomain inhibitor or an ALK inhibitor have been unsuccessful in neuroblastoma." (PMID 39001383, 2024). "A recent phase 1 trial of lorlatinib for patients with ALK-driven refractory or relapsed neuroblastoma showed relatively high response rates." (PMID 39177282, 2024). "Recently it has been more precisely defined that RET hyperactivation is driven by ALK in neuroblastoma." (PMID 38666930, 2024). "We also report major, long-lasting clinical responses to lorlatinib as monotherapy in five patients with ALK-driven relapsed or refractory neuroblastoma." (PMID 39177282, 2024). "Isogenic human stem cell models thus represent a clean system to elucidate the mechanism by which ALK and MYCN cooperate in high-risk neuroblastoma." (PMID 38451815, 2024). "We present five patients with ALK-driven relapsed or refractory neuroblastoma treated with lorlatinib as monotherapy." (PMID 39177282, 2024). "The ALK gene has emerged as a significant player in neuroblastoma development, making it an attractive target for therapeutic interventions." (PMID 38397899, 2024). "Mutations in the ALK tyrosine kinase domain commonly arise in tumors resistant to ALK TKI treatment and have been reported in patients with neuroblastoma treated with ALK inhibitors." (PMID 39177282, 2024). "Goldsmith and colleagues recently published data from a phase 1 clinical trial (NANT2015-02) with lorlatinib monotherapy in relapsed or refractory ALK-driven neuroblastoma, showing an overall response rate of 30% in children and 67% in adults." (PMID 39177282, 2024). "In a panel of human neuroblastoma cell lines harboring different ALK genomic status, the ALK inhibitors suppressed LPA-induced phosphorylation of extracellular signal-regulated kinases 1/2 (ERK1/2), which are major regulators of cell proliferation." (PMID 38927035, 2024). "Researchers detected decreased ALK phosphorylation, specifically in neuroblastoma cells that depend on ALK for survival, when employing tunicamycin, a substance renowned for broadly disrupting glycosylation." (PMID 38397899, 2024). "Although ALK fusions are less common in other tumor types, they have been occasionally detected in sarcomas, neuroblastoma, and esophageal, renal, breast, ovarian, thyroid, and colorectal cancers." (PMID 39906487, 2024). "In neuroblastoma and neuroendocrine prostate cancer, activation of the anaplastic lymphoma kinase (ALK) receptor tyrosine kinase up-regulates MYCN transcription through a STAT3-dependent mechanism." (PMID 38748789, 2024). "A previous study by Berko and colleagues made use of NGS panels covering 62 or 324 cancer-related genes for ctDNA analysis in patients with relapsed or refractory ALK-driven neuroblastoma treated with lorlatinib." (PMID 39177282, 2024). "Most neuroblastomas express the full‐length ALK receptor, and high expression of ALK correlates with poor prognosis." (PMID 38877641, 2024). "While strong evidence links full-length ALK expression to neuroblastoma, the significance of ALK receptor expression in other tumor types remains poorly understood." (PMID 38339401, 2024). "Ultimately, this research underscores the complexity of ALK behavior and its implications for targeted therapies in neuroblastoma treatment." (PMID 38397899, 2024). "In a study addressing mechanisms imparting resistance to ALK inhibitors in eight different lines of neuroblastoma cells, EC50 values for decreases in cell viability varied from 10 to 100 nM in five cell lines and ranged around 1 μM in three others." (PMID 37658212, 2024).
neuroblastoma (continued). "Targeting oncogenic ALK activity in neuroblastoma is an attractive therapeutic strategy but success has been limited by resistance to ALK inhibitors." (PMID 38653965, 2024). "The LPA effects and the participation of the tyrosine kinase receptor anaplastic lymphoma kinase (ALK) in LPA mitogenic signaling were studied in human neuroblastoma cell lines." (PMID 38927035, 2024). "Patient 1 presented with a stage M, ALK p.R1275Q-positive neuroblastoma at 9 years of age and had a metastatic relapse in the mediastinum, lungs, and hip bone 2 years after the initial diagnosis." (PMID 39177282, 2024). "Activating mutations of full‐length ALK are found in 8%−12% of neuroblastomas, including familial neuroblastoma, and ALK amplification is found in 2%−3% of neuroblastomas, increasing the risk of relapse." (PMID 38877641, 2024). "However, as tunicamycin might not be suitable for clinical use, the study’s findings emphasize a proof-of-concept, prompting further exploration into alternative approaches targeting N-linked glycosylation as a potential strategy for ALK-dependent neuroblastoma treatment." (PMID 38397899, 2024). "This implies potential usefulness of adding an adjunctive IC Regimen to lorlatinib treatment of other ALK positive cancers like glioblastoma or neuroblastoma." (PMID 39056757, 2024). "There have been case reports of response to ALK TKIs in patients with colorectal, myxoid uterine, thyroid, neuroblastoma and pancreas cancers." (PMID 39188081, 2024). "We report a neuroblastoma-ALK (NB-ALK) sequencing panel that enables ultrasensitive and highly specific detection of ALK-mutational positive ctDNA in patients with neuroblastoma treated with ALK TKIs." (PMID 39177282, 2024). "In neuroblastoma, ETV5 drives tumor aggressiveness through transcriptional regulation mediated by activated ALK mutations and is influenced by the MAPK signaling pathway, a mechanism consistent across different cancer types." (PMID 38515748, 2024). "Consistent with FN1 as a marker of mesenchymal neuroblastoma,2ALK/MYCN tumors were more mesenchymal than MYCN tumors, suggesting that ALK can bias neuroblastoma toward the mesenchymal cell state." (PMID 38451815, 2024). "The Negr1-derived peptide demonstrated the ability to degrade ALK and slow tumor growth both in vitro and in vivo, presenting a promising avenue for treating aggressive neuroblastoma resistant to current ALK inhibitors." (PMID 38397899, 2024). "Combining ALK and Wnt inhibitors showed potential against NEPC and neuroblastoma, underscoring ALK’s significance and proposing a therapeutic strategy targeting both ALK and Wnt pathways in ALK-related tumors, linking insights between NEPC and neuroblastoma." (PMID 38397899, 2024). "It follows that the farnesyltransferase inhibitor (FTI) lonafarnib in addition to ALK TKIs act synergistically in neuroblastoma, inducing apoptosis in vitro." (PMID 38653965, 2024). "ALK TKIs have emerged as promising targeted therapy in ALK-driven neuroblastoma, although primary or acquired resistance to treatment occur frequently." (PMID 39177282, 2024). "Activated ALK promoted upregulation of FN1 and POSTN in our human stem cell model and in patients with amplified or mutant ALK neuroblastoma." (PMID 38451815, 2024). "ALK is the major player involved in the onset of neuroblastoma, a cancer of the sympatho-adrenal lineage which mostly affects children aged 5, or younger." (PMID 38874999, 2024). "Adult patients with advanced or metastatic• Cohort 1: Inflammatory myofibroblastic tumors• Cohort 2: Neuroblastoma,• Cohort 3: other tumours with ALK alterations." (PMID 38807312, 2024).
neuroblastoma (continued). "Our results support the use of lorlatinib as monotherapy in ALK-driven neuroblastoma and suggest that ctDNA analysis using the NB-ALK sequencing panel is effective for evaluation of treatment response and early detection of relapse in these patients." (PMID 39177282, 2024). "The ALK.CAR-T cells were also cytotoxic to human neuroblastoma cell lines and primary tumor samples in vitro." (PMID 38688910, 2024). "This action effectively obstructs cell cycle progression and proves to be an effective means for overcoming resistance to ALK inhibitors in human neuroblastoma." (PMID 38283176, 2024). "Regular and accurate evaluation of tumor burden is crucial to provide the optimal treatment during the different phases of disease in patients with ALK-driven relapsed or refractory neuroblastoma." (PMID 39177282, 2024). "This combination also activated the wnt/β-catenin pathway; however ALK cleavage by MMP-9 in neuroblastoma results in β-catenin release from ALK." (PMID 38397899, 2024). "Given the heterogeneity of HRNBL, especially in the relapsed setting, agents that target a subset of neuroblastoma such as ALK inhibitors will also play a critical role." (PMID 37835416, 2023). "Here, we investigated IGF1R in ALK-driven neuroblastoma, with the aim of understanding its contribution and exploring its potential for targeted therapy." (PMID 37686528, 2023). "Here we describe that Negr1-derived peptides induce ALK downregulation and reduce neuroblastoma progression in vitro and in vivo." (PMID 37765276, 2023). "To assess ALK alterations in neuroblastoma at relapse or progression, we investigated ALK SNV and amplification in 198 and 172 tumors, respectively." (PMID 36807339, 2023). "A panel of 12 neuroblastoma cell lines with ALK mutant (ALKmut) or wild-type (ALKwt) status were selected to assess sensitivity to SHP2 inhibition." (PMID 38032104, 2023). "Inclusion of this agent is supported by data from a phase 1 study (NANT 1502, NCT03107988) in which patients with ALK aberrant recurrent or refractory neuroblastoma tolerated the combination of lorlatinib with chemotherapy and demonstrated a clinical response." (PMID 37760578, 2023). "We performed a metabolic activity screen with 14 clinically approved drugs targeting a wide range of cancer‐ and neuroblastoma‐relevant pathways, such as ALK, MAPK, and PI3K, to identify agents that can overcome VCR resistance." (PMID 36181342, 2023). "Here, we show that SHP2 inhibitors SHP099 and TNO155 show higher selectivity in ALK-mutant neuroblastoma cells compared with those with wild-type status." (PMID 38032104, 2023). "AEs such as peripheral neuropathy, peripheral edema and CNS effects reported in adults with ALK fusion NSCLC20–22 were more frequently observed in adults with neuroblastoma compared to children." (PMID 37012551, 2023). "In contrast to SNV and amplification, translocation of ALK has been reported only occasionally in neuroblastoma." (PMID 36807339, 2023). "Early work has suggested that crizotinib, an oral inhibitor of ALK, has clinical activity in neuroblastoma patients whose tumors overexpress ALK protein in the absence of either ALK gene mutations or gene fusions." (PMID 36619485, 2023). "Targeting neuroblastoma with single-agent ALK-TKIs has shown efficacy in subsets of patients; however, tumor resistance commonly occurs." (PMID 38032104, 2023). "This combination has shown potential to enhance outcomes for patients diagnosed with ALK-positive neuroblastoma." (PMID 37998328, 2023). "Genomic alterations of the anaplastic lymphoma kinase gene (ALK) occur recurrently in neuroblastoma, a pediatric malignancy of the sympathetic nervous system." (PMID 36807339, 2023). "We conducted a first-in-child study evaluating lorlatinib with and without chemotherapy in children and adults with relapsed or refractory ALK-driven neuroblastoma." (PMID 37012551, 2023).
neuroblastoma (continued). "ALK cell signalling has been studied predominantly in the context of the oncogenic effects of expressed fusion proteins in cancers other than neuroblastoma (e.g., NSCLC)." (PMID 37414143, 2023). "Despite massively divergent regulatory mechanisms, ALK, PIM and Aurora kinases all obtain significant roles in cellular glycolytic and mitochondrial metabolism and neuroblastoma progression, and in several instances are implicated in treatment resistance." (PMID 37414143, 2023). "In fact, drugs targeting specific molecular aberrations in neuroblastoma are under active development and ALK inhibitors are the most notable examples because they are frontline treatment options." (PMID 37046647, 2023). "The ALK inhibitor crizotinib has already been used with variable efficacy in pediatric solid cancer, including neuroblastoma." (PMID 37213274, 2023). "Anaplastic lymphoma kinase (ALK) amplification is found in 2–3% of neuroblastoma and occurs frequently together with MYCN amplification." (PMID 37765276, 2023). "Although the RAS‐MAPK pathway is hyperactivated in ALK‐addicted neuroblastoma cells, these cells are resistance to MAPK inhibitors due to a feedback response mediated by SIN1." (PMID 37877351, 2023). "•Divergent protein kinases ALK, PIM and Aurora are implicated in neuroblastoma progression and treatment resistance." (PMID 37414143, 2023). "Alternatively, some neural crest pathologies, including neuroblastoma, involving ALK activity and LIN28B gene expression were studied in the Xenopus model." (PMID 37444423, 2023). "Although neuroblastoma can develop resistance to ALK inhibitors too, the resistance mechanisms involved create other vulnerabilities, such as hypersensitivity to MEK inhibition." (PMID 37046647, 2023). "In comparison to wild-type, ALK-mutant neuroblastoma cell lines were more sensitive to SHP2 inhibition with TNO155." (PMID 38032104, 2023). "Here, we have assessed the efficacy of the SHP2 inhibitor TNO155 alone and in combination with the ALK-TKIs crizotinib, ceritinib, or lorlatinib for the treatment of ALK-driven neuroblastoma using in vitro and in vivo models." (PMID 38032104, 2023). "Cells with these mutations respond to lorlatinib in pre-clinical studies, providing the rationale for a first-in-child Phase 1 trial (NCT03107988) in patients with ALK-driven neuroblastoma." (PMID 37147298, 2023). "The anaplastic lymphoma kinase (ALK) is a tyrosine kinase receptor mainly expressed in neural tissues during embryonic development, but also in neuroblastoma, the most common extracranial childhood solid tumor." (PMID 38139220, 2023). "In neuroblastomas, DNA repair genes and players in transcriptional regulation were mostly altered in addition to ALK and N-MYC." (PMID 36914906, 2023). "The tyrosine kinase inhibitor (TKI) Crizotinib has shown to be effective in treating ALK-aberrant neuroblastoma." (PMID 37835416, 2023). "The clinical studies of crizotinib and ceritinib for patients with refractory or relapsed ALK-driven neuroblastoma showed responses that were limited mainly to tumors harboring an ALK R1275 mutation with no activity in tumors harboring an F1174 mutation." (PMID 37012551, 2023). "ALK inhibitors have been used in the treatment of neuroblastoma, and they lead to target upregulation, potentially further increasing efficacy of CAR T-cell targeting." (PMID 36831514, 2023). "An elegant study by Debruyne and colleagues demonstrated that ALK-mutated, MYCN-amplified neuroblastoma cells that develop resistance to ALK inhibition had elevated BORIS expression and altered chromatin looping interactions." (PMID 36980267, 2023). "The initiation and development of neuroblastoma are underpinned by crucial genetic factors, including but not limited to MYCN amplifications, MDM2 amplifications or overexpression, ALK mutations or amplifications, and segmental chromosomal abnormalities." (PMID 37834394, 2023).
neuroblastoma (continued). "The full landscape of ctDNA genomic alterations in patients with ALK-driven refractory or relapsed neuroblastoma treated on this trial is detailed in a companion manuscript." (PMID 37012551, 2023). "Genome-wide CRISPR activation screens of neuroblastoma cells treated with ALK inhibitors brigatinib or ceritinib for 14 days identified Pim1 as a resistance gene, due to an anti-apoptotic phosphorylation of BAD by PIM1." (PMID 37414143, 2023). "The treatment with Negr1 protein and derived peptides induce ALK downregulation and halt neuroblastoma progression in vitro and in vivo." (PMID 37765276, 2023). "To date, this is the first evidence demonstrating changes in neuroblastoma invasion and potentially metastasis in response to treatment with drugs targeting both ALK and SHP2." (PMID 38032104, 2023). "The ALK inhibitors crizotinib and ceritinib have been evaluated in early clinical trials in neuroblastoma and other pediatric malignancies, showing promising clinical activity in a fraction of cases." (PMID 36807339, 2023). "While PNET is a distinct entity from neuroblastoma, there are shared biological and molecular characteristics that make the finding of oncogenic ALK expression less surprising in the case presented here." (PMID 36619485, 2023). "This is in keeping with reports of loss of NF1 function causing relapse in neuroblastoma, and the contribution of NF1 mutations to ALK inhibitor resistance." (PMID 37414143, 2023). "Deregulated expression of full-length ALK has also been observed in some primary solid tumors including ovarian high-grade serous carcinoma, uterine carcinosarcoma, neuroblastoma, glioblastoma, and melanoma." (PMID 37592266, 2023). "The most common genetic alterations in neuroblastoma are MYCN amplification, anaplastic lymphoma kinase (ALK) mutations, segmental chromosomal alterations, and DNA copy number alterations." (PMID 37213274, 2023). "ALK amplifications occurred only in stage 3 (4/28, 14.3%) and stage 4 (10/234, 4.3%) neuroblastomas, and were significantly enriched in stage 3 compared to non-stage 3 tumors (14.3% versus 3.7%, P = 0.032)." (PMID 36807339, 2023). "We here provide a detailed view on the development of genomic ALK alterations in neuroblastoma over the course of the disease." (PMID 36807339, 2023). "Truncated mutations are formed by elimination of the extracellular domain of ALK gene which lead to activation of downstream pathways and have been identified in neuroblastoma, squamous cell carcinoma of the skin and melanomas." (PMID 37773318, 2023). "Somatic and germline gene aberrations, leading to ALK activation, are also present in this disease and were reported in familial and sporadic neuroblastoma." (PMID 38139220, 2023). "Overall, our studies provide in vitro and in vivo support for single-agent TNO155 treatment in neuroblastoma and demonstrate the efficacy and tolerability of TNO155 combinations with ALK-TKIs in several ALK-mutant neuroblastoma models." (PMID 38032104, 2023). "ALK is commonly mutated in primary and relapsed neuroblastoma tumors and ALK tyrosine kinase inhibitors (TKI) are promising treatments for ALK-driven neuroblastoma; however, innate or adaptive resistance to single-agent ALK-TKIs remain a clinical challenge." (PMID 38032104, 2023). "The anaplastic lymphoma kinase (ALK) is present in neuroblastoma, pancreatic and breast cancer, and melanoma and has been found to be a rate-limiting factor for the development of glioblastoma, communicating through the IRS proteins." (PMID 37834454, 2023). "MAPK inhibition increased SIN1 phosphorylation on T86, enhancing AKT activation and resulting in increased ALK‐addicted neuroblastoma cell survival and growth." (PMID 37877351, 2023). "Considering the high incidence of putative de novo ALK point mutations at relapse and their potential therapeutic consequences, we suggest to determine the genomic ALK status in all neuroblastoma cases at relapse or progression." (PMID 36807339, 2023).